UNK (unk zinc finger)
Description:
Sequence-specific RNA-binding protein which plays an important role in the establishment and maintenance of the early morphology of cortical neurons during embryonic development. Acts as a translation repressor and controls a translationally regulated cell morphology program to ensure proper structuring of the nervous system. Translational control depends on recognition of its binding element within target mRNAs which consists of a mandatory UAG trimer upstream of a U/A-rich motif. Associated with polysomes.
Synonyms: KIAA1753; ZC3H5; ZC3HDC5; UNKEMPT
Tractability: PROTAC: ubiquitination databases record sites on it; its protein half-life has been measured.
Gene: Protein-coding gene on chromosome 17 (75,784,806 to 75,825,799, forward strand). Ensembl gene ENSG00000132478.
Subcellular location: Cytoplasm
Subcellular location (Human Protein Atlas): Cytoplasmic bodies; Cytosol
Gene Ontology:
Molecular function: mRNA CDS binding; RNA binding; metal ion binding; ribosome binding
Biological process: cell morphogenesis involved in neuron differentiation; negative regulation of cytoplasmic translation
Cellular component: cytoplasm; cytosol
Genetic constraint (gnomAD): Loss-of-function variants: 31 observed, 87.22 expected, observed/expected ratio (o/e) 0.36, 90% interval 0.27 to 0.48. The upper end of that interval is the gene's LOEUF score, 0.48, which puts it in group 2 of 6, group 1 being the genes least tolerant of losing a copy. Missense variants: 751 observed, 1,036.1 expected, observed/expected ratio (o/e) 0.72, 90% interval 0.68 to 0.77. Synonymous variants: 436 observed, 429.9 expected, observed/expected ratio (o/e) 1.01, 90% interval 0.94 to 1.1.
Homologues: Orthologues: chimpanzee UNK (100% identical), macaque UNK (99% identical), pig UNK (98% identical), dog UNK (98% identical), rabbit UNK (97% identical), guinea pig UNK (97% identical), mouse Unk (95% identical), rat Unk (95% identical), tropical clawed frog unk (78% identical), zebrafish unk (58% identical), Drosophila melanogaster unk (38% identical), Caenorhabditis elegans unk-1 (31% identical). Paralogues in human: UNKL (50% identical).
Diseases named in the same sentence as UNK in open-access papers:
UNK is named in the same sentence as 10 diseases in open-access papers, as found by Europe PMC text mining. Sharing a sentence is not in itself a finding about the gene and the disease. The quoted sentences say what the papers report.
endometriosis (2 papers, 2020 to 2021). The growth of functional endometrial tissue in anatomic sites outside the uterine body. "OR calculations did not indicate an effect of endometriosis or increased levels of uNK on an abortion prior to the examination [OR = 1.0776/1.3952; 95% confidence interval (CI) 0.5782–2.0084/0.6924–2.8112; P = 0.8140/0.8140]." (PMID 32666129, 2020). "In 11 patients with elevated uNK neither endometriosis, nor RIF or RPL have been reported." (PMID 32666129, 2020).
intrauterine growth restriction (2 papers, 2017 to 2022). "In these uMC/uNK-deficient mice, we observed nearly un-remodeled SAs and drastic effects on pregnancy outcome and the progeny, with more than half of the fetuses affected by intrauterine growth restriction (IUGR)." (PMID 28670317, 2017).
female sterility (1 paper, 2020). "The Y-specific genes (INP1, ETOL1, UNK, and UAP56) are not expressed at the stage where ovule abortion occurs and are unlikely candidates for female sterility." (PMID 32892750, 2020).
Miscarriage (1 paper, 2021). A pregnancy that ends at a stage in which the fetus is incapable of surviving on its own, defined as the spontaneous loss of a fetus before the 22th week of pregnancy. "Using endometrial biopsy analysis, a study evaluated uNK abundance in the endometrium of women with idiopathic recurrent miscarriage (IRM) compared to fertile women and found that uNK was increased in IRM patients, suggesting a uNK role in the pathophysiology of recurrent miscarriage." (PMID 33544456, 2021).
Obesity (1 paper, 2020). Accumulation of substantial excess body fat. "Future research designed to test if indeed a two-hit-like hypothesis (i.e., obesity + infection) potentiates uNK cytotoxicity will be necessary to promote understanding of this phenomenon." (PMID 32471078, 2020).
osteoarthritis (1 paper, 2021). A noninflammatory degenerative joint disease occurring chiefly in older persons, characterized by degeneration of the articular cartilage, hypertrophy of bone at the margins and changes in the synovial membrane. "Downregulation of UNK at the RNA and protein levels in high-grade osteoarthritis cartilage in humans suggests a role in disease pathogenesis." (PMID 33473114, 2021).
cancer (1 paper, 2025). A tumor composed of atypical neoplastic, often pleomorphic cells that invade other tissues. "While DDX46 functions as an RNA splicing factor similar to DDX42, detailed reports on the biological functions of SMNDC1 and UNK in cancer are currently limited." (PMID 40831000, 2025).
reproductive diseases (1 paper, 2025). "High uNK levels have been examined in reproductive diseases, but low levels remain underexplored." (PMID 40003650, 2025).
UNK also shares sentences with these, for which no sentence is quoted: angioedema (2 papers); preeclampsia (2).